ABCB5 (ATP binding cassette subfamily B member 5)
Diseases named in the same sentence as ABCB5 in open-access papers (continued):
Sharing a sentence is not in itself a finding about the gene and the disease.
tumor (continued). "Furthermore, ABCB5+ and ABCB5- cells purified by flow cytometry using 3C-1D12 antibody had similar tumorigenic capacities and were able to restore tumor heterogeneity in mouse xenograft models transplanted with Matrigel." (PMID 39267923, 2024). "In vivo genetic genealogy tracing demonstrated the specific ability of the ABCB5(+) subpopulation to self-renew and differentiate compared to ABCB(-), as ABCB(+) cancer cells produced both ABCB5(+) and ABCB5- progeny, whereas the ABCB5(-) tumor population produced only ABCB5(-) cells." (PMID 39611156, 2024). "Interestingly, a comparison of CMCs with corresponding tumor tissue revealed that ABCB5 and RANK expression is more attributed to CMCs than the tumor itself." (PMID 34575876, 2021). "Interestingly, ABCB5 was strongly expressed in 90% of tumours (average expression intensity 2.7 ± 0.5)." (PMID 34885099, 2021). "Nonetheless, the paralleled blood and tumour DNA sequences from HCC patients indicated that ABCB5 mutation in tumours was not common and corroborated the TCGA data sets." (PMID 32783366, 2020). "Besides, ABCB5 was critical to tumor vascular invasion and the ABCB5-dependent metastatic propensity was found to be dependent on IL-8/AXL signaling." (PMID 32357409, 2020). "Our study revealed that the ABCB5 sequence variation was germline, whereas tumour mutation event was not common." (PMID 32783366, 2020). "It has been shown that high ABCB5 expression was significantly related to tumor formation, metastasis and recurrence in OSCC and ABCB5 was co-labeled with CD44 (oral CSC marker), suggesting ABCB5 was associated with oral CSCs and multistep carcinogenesis of OSCC." (PMID 32357409, 2020). "ABCB5 and Lgr5 and to lesser extent CD133 and CK20 genes were significantly expressed in the analyzed cells from bone marrow aspirates while only ABCB5 and Lgr5 were significantly negative associated with tumor progress and overall survival." (PMID 34221246, 2017). "We could show that ABCB5 expression in the bone marrow from patients with CRC was strongly dependent on tumor grading and wall infiltration." (PMID 34221246, 2017). "Importantly, VEGF-R1 knockdown reduced ABCB5-induced tumor growth and blocked the development of ABCB5+ vascular mimicry morphology." (PMID 29156643, 2017). "Indeed, ABCB5+ MICs have been shown to induce immune responses less efficiently than the ABCB5− bulk of the tumor." (PMID 27764776, 2016). "Tumor growth upon ABCB5 inhibition was severely impaired throughout the course of the experiment." (PMID 26910836, 2016). "Also, an anti-ABCB5 antibody has been used to treat melanoma in a xenograft model resulting in reduction in tumor size and tumor eradication in 70 % of treated animals." (PMID 23314952, 2013). "When examining the ABCB5 mRNA expressing cell lines, we found a significantly higher proportion of ABCB5+ cells in the WM-266-4 cell line that originates from a metastasis, compared to the WM-115 cells from the primary tumor of the same patient." (PMID 22675422, 2012). "While our in vivo study demonstrated a correlation between ABCB5 expression and tumor progression, future studies using ABCB5 knockdown or knockout approaches in in vivo models to provide mechanistic insights into its role in tumor progression should be addressed." (PMID 40746888, 2025). "Moreover, treatment, like temozolomide, can enrich ABCB5-expressing cells, suggesting that conventional therapies may inadvertently select for more resistant tumor cell populations." (PMID 40867277, 2025). "Moreover, sanguinarine and other BZD inhibited the P-glycoprotein/ABCB1 and related ABCB5 in drug resistance in multidrug-resistant tumor lines, increasing their sensitivity to cytotoxic drugs, which might allow for better treatments." (PMID 35209167, 2022).
tumor (continued). "The presence of an EMT signature in the ABCB5 CTC fractions indicates that activation of this signature might play a critical role either in the migration of these CTCs from the tumour or in their ability to seed new tumours." (PMID 30769764, 2019). "ABCB5 promotes angiogenesis, EMT, and tumor metastasis by activating the Hedgehog, Notch, and Wnt pathways." (PMID 40746888, 2025). "This is reminiscent of the ABCB5 gene, where its expression seems to mark slow-cycling, MITF-high tumor-initiating cells with a more differentiated phenotype." (PMID 40528051, 2025). "This suggests the involvement of ABCB5+ and CD133+ cells in tumour growth and progression by promoting vasculogenic mimicry and morphogenesis of tumour microcirculation." (PMID 35740696, 2022). "In a landmark study, ABCB5 was shown to be a marker of skin progenitor cells and malignant melanoma-initiating cells (MMIC), regulating tumor initiation and progression in nude mice." (PMID 32587767, 2020). "Genomic DNA was extracted from tumour samples of 20 out of 300 HCC patients, and a total of 28 exons and exon‐intron boundaries of ABCB5 gene were amplified by polymer chain reaction (PCR)." (PMID 32783366, 2020). "In surviving 4T1 tumor cells in Abraxane or anti-PD1-treated mice, nuclear DUSP6 was enriched in both triple-positive cells (CSV+ABCB5+DUSP6+) and the double-positive ABCB5+DUSP6+ tumor cell pool." (PMID 31238530, 2019). "This approach identified a total of 11 and 10 genes expressed in single tumour cells that were overexpressed in the MCSP- and ABCB5-enriched CTC fractions, respectively." (PMID 30769764, 2019). "Interestingly, we showed that ABCB5 is expressed only by rare subpopulations within patient-matched tumour tissues, supporting the hypothesis that CTCs are derived from rare subpopulations in the tumour with the potential to initiate metastases." (PMID 30769764, 2019). "None of 22 heterogeneously expressed membrane markers, including ABCB5 and CD271, were able to enrich for tumor-initiating cells." (PMID 29156643, 2017). "In this study, the expression of VEGFR1 and its downstream signaling play a crucial role in ABCB5+ MMIC which govern the vasculogenic mimicry (VM) and higher tumor growth." (PMID 28137308, 2017). "The differential expression of these genes reveals their possible involvement in different aspects of tumor biology, suggesting that ABCA10 and ABCB5 may play distinct and opposing roles in cancer development and progression." (PMID 40445912, 2025). "In addition to the deregulation of aberrant signaling pathways for tumor growth and survival, MSCs are notable for their expression of CD20, CD133, CD166, CD271, ABCB5, Nestin, and CD105 surface markers." (PMID 38334632, 2024). "In an orthotopic mouse model of conjunctival melanoma, ABCB5 expression, analyzed by flow cytometry using the 3C2-1D12 antibody which is not commercially available, increased during tumor expansion phases and its expression was higher in metastasis." (PMID 39267923, 2024). "Furthermore, a stem cell marker that is frequently found co-expressed with ABCB5, CD133, was also expressed in tumourigenic, tumour-initiating cells." (PMID 35740696, 2022). "In tumor cells isolated from TNBC xenografts, targeting the nPKC-θ axis significantly reduced the expression of nuclear localized PKC-θ in addition to several key CSC-like mesenchymal markers including CSV, ABCB5, ALDH1, and CD133/1." (PMID 35326747, 2022). "Together, these data demonstrated a favorable biosafety profile of GMP-manufactured ABCB5+ MSCs in terms of distribution to non-target tissues, toxicity, ectopic tissue formation, or tumor development." (PMID 36613507, 2022). "In our preclinical tumorigenicity study, we did not detect any macro- or micropathological signs of tumor formation in NSG mice after repeated subconjunctival injections of ABCB5+ LSCs up to 20 weeks." (PMID 33741066, 2021).
tumor (continued). "As shown in this study, the clinically established MDR conferring proteins (P-gp, BCRP, ABCB5 and ΔEGFR) did not hamper BetA activity in tumor cells." (PMID 29867487, 2018). "In addition, most patients with a cluster of genes for ABCB5, Lgr5, and CD133 were derived from group I that developed metastases and/or died tumor related." (PMID 34221246, 2017). "First, ABCB5 blockage mediated by VNP20009 may render cells more sensitive to chemotherapy agents, therefore CTX kills CSCs as well as other tumor cells." (PMID 26910836, 2016). "Although three specific patterns were detected, ABCB5 expression in OSSN presented most often as a non-specific pattern through the whole thickness of the tumor." (PMID 26843453, 2016). "Our results showed that the expression of ABCB5 was decreased in the tumor of mice treated with VNP-shABCB5, which indicated that VNP-mediated shRNA could specifically target ABCB5 and silence its expression." (PMID 26910836, 2016). "Moreover, ABCB5-positive cells contribute to the formation of an immunosuppressive microenvironment by secreting cytokines (IL-6, IL-8, TGF-β) and expressing immune checkpoint ligands, such as PD-L1, thereby favoring tumor progression and a poor prognosis." (PMID 41681896, 2026). "Additionally, ABCB5 modulates immune cell behavior in the TIME, influencing the differentiation and migration of macrophages and T-cells, thereby creating an environment that favors tumor growth and resistance to immunotherapy." (PMID 40445912, 2025). "In addition, the development of tumor heterogeneity in melanoma is the result of differential expression in the same tumor to various functional proteins, such as stem cell markers CD20, CD133, ABCB5, CD271, JARID1B, and ALDH1." (PMID 38334632, 2024). "Beyond CD56 ADC targeting, ABCB5 blockage with an anti-ABCB5 mAb has also shown efficacy in reducing MCC drug resistance to carboplatin and etoposide in vivo, attenuated xenograft growth, and increased caspase 3 expression in mice injected with MKL-1 tumor cells." (PMID 39456853, 2024). "Following this, we characterised the molecular phenotype of these tumours by examining the fluorescent intensity of several EMT, stem-like, and resistance markers, namely Snail, EGFR, cell-surface vimentin (CSV), ALDH1A and ATP-binding cassette sub-family B member 5 (ABCB5)." (PMID 29311580, 2018). "LSD1-s111p was enriched in chemoresistant mesenchymal tumour cells after cytotoxic monotherapy, where it may play a role in chemotherapeutic resistance as suggested by our data demonstrating an increase in EGFR, ALDH1A and ABCB5 in these cells." (PMID 29311580, 2018). "The gene expression of ABCB5 in comparison to CD133 (molecule for identifying cancer initiating cells), Lgr5 (an intestinal stem cell marker) as well as Cytokeratin (CK) 20 (terminally differentiated tumor cells of epithelial origin) in these cells was evaluated." (PMID 34221246, 2017). "Given the limited sample and the various expression patterns of ABCB5 observed in this study, the relationship between ABCB5 expression and tumor progression could not be properly evaluated." (PMID 26843453, 2016). "We hypothesized that ABCB5 might not be involved in the chemoresistance mechanism of tumor cells in OSSN, but more work is needed to conclusively establish this." (PMID 26843453, 2016). "Although targeting ABCB5 by small short interfering RNA delivered by VNP20009 failed to inhibit tumor growth, the combined treatment of VNP-shABCB5 and chemotherapy can act synergistically to delay tumor growth and enhance survival time in a primary B16F10 mice model." (PMID 26910836, 2016). "However, cells from the ABCB5-negative population exhibited a six fold reduction of tumor-initiation frequency." (PMID 26910836, 2016).
tumor (continued). "This evidence is consistent with the interpretation that the metabolic profile of ABCB5-expressing cells and, potentially, multidrug-resistant cells and CSCs in general, is more tumor-like than that of cancer cells that are neither CSCs nor express MDR proteins." (PMID 27560924, 2016). "Hence, the absence of ABCB5 positive cells two months after PEF administration supports the tumor-free skin regeneration process." (PMID 25965851, 2015). "Cellular plasticity of tumor-initiating cells represents a proposed mechanism that leads to intra-tumor heterogeneity as they are thought to be capable to enter, exit and to re-enter a stem-cell state while changing their phenotype defined by expression of cell surface markers like CD271 or ABCB5." (PMID 24799129, 2014). "ABCB5 and CD271 may be useful markers for targeting tumour initiating CMCs." (PMID 22978632, 2012). "Interestingly, the three tumor cell lines that overexpress three ABC transporters, P-gp, BCRP and ABCB5 did not confer resistance to BetA." (PMID 29867487, 2018).
cancer (64 papers, 2010 to 2025). A tumor composed of atypical neoplastic, often pleomorphic cells that invade other tissues. "Studies should also look into the processes underlying cancer-specific changes and confirm the context-dependent expression of ABCB5 in different cohorts." (PMID 40445912, 2025). "Conversely, ABCB5 demonstrates a strong association with chemoresistance and immune suppression, driven by its role in regulating cancer stemness and IL-1β/IL-8/CXCR1 signaling loops." (PMID 40445912, 2025). "In conjunction with its role as a marker of CSCs, ABCB5 has been associated with cancer progression in several cancer types." (PMID 39267923, 2024). "One of the genes whose increased expression is linked to greater cancer aggressiveness and drug resistance is ABCB5." (PMID 36431795, 2022). "Following gene-based burden testing and after correction for multiple testing, two of these genes, ABCB5 and C16orf96, were determined to show statistically significant association with cancer." (PMID 31053105, 2019). "The significant enrichment of the apical junction hallmark in ABCB5 CTCs is interesting as loss of cell polarity represents a step towards EMT cancer." (PMID 30769764, 2019). "Similarly, a positive correlation between ABCB5 expression and cancer-associated fibroblasts was observed in most tumors, except for TGCT." (PMID 40445912, 2025). "Furthermore, the apparent correlation of ABCA10 and ABCB5 with cancer-associated fibroblasts across tumors highlights their broader influence on TIME." (PMID 40445912, 2025). "In various cancers, 134 missense mutations and 20 truncating mutations were detected in ABCB5." (PMID 39267923, 2024). "However, the underlying mechanisms leading to the overexpression of ABCB5 in human cancers remain poorly understood." (PMID 32783366, 2020). "Hence, specific ABCB5 genetic variants were associated with different cancer risks." (PMID 32783366, 2020). "In the ABC transporters module, we observed significant upregulation of multidrug efflux pumps that have previously been reported to be upregulated by GH in other cancers: ABCB5 and ABCB1 in both sexes and ABCG2 in males only." (PMID 40806252, 2025). "Our research demonstrated that ABCA10 shows reduced expression, while ABCB5 displays variable expression patterns across tumors, indicating their opposing roles and flexible functions in pan-cancer." (PMID 40445912, 2025). "Although ABCB5 has been extensively studied in cancer biology, emerging evidence suggests that it is also expressed by normal cells." (PMID 39941329, 2025). "By utilizing tools like CRISPR/Cas9, ABCB5+ MSCs can serve as carriers for therapeutic genes, addressing genetic disorders, such as hereditary skin diseases and cancers." (PMID 39941329, 2025). "It has been indicated that overexpression of ABCB5 was closely related to poor prognosis in various cancers." (PMID 40746888, 2025). "Given the importance of ABCB5 in human cancer biology, we explored the expression of this pump at the protein level in HeLa cells treated with close the IC50 of VPA." (PMID 41020871, 2025). "Conversely, ABCB5 expression exhibited a positive correlation with DCs and macrophages across most cancer types." (PMID 40445912, 2025). "Our in-depth bioinformatics exploration highlights the pivotal roles of ABCA10 and ABCB5 genes across a spectrum of cancers, offering insights into potential cancer biomarkers." (PMID 40445912, 2025). "Unlike ABCA10, multiple studies have demonstrated the overexpression of ABCB5 across various cancer types, highlighting its significant role in promoting chemoresistance." (PMID 40445912, 2025). "We utilized an innovative bioinformatics approach to bridge this significant gap by simultaneously examining ABCA10 and ABCB5 across multiple cancer types." (PMID 40445912, 2025). "ABCB5 plays a critical role in cancer outgrowth, particularly in CRC, where it has been established as a vital element in mediating patient resistance to doxorubicin chemotherapy." (PMID 39679367, 2024).